BDNF (brain derived neurotrophic factor)
Diseases named in the same sentence as BDNF in open-access papers (continued):
Sharing a sentence is not in itself a finding about the gene and the disease.
depression (continued). "However, when hierarchical diagnostic criteria for depression was used as the output variable, the SS SLC6A4 genotype (but not BDNF) was a predictor of major depression (Wald's statistic 5.8, P = 0.016, CI = 1.1–2.7)." (PMID 24683520, 2014). "In addition, mice with adulthood BDNF knock down do not show any baseline depression-like behaviors in behavioral despair models, however, antidepressant-like effects are lost." (PMID 24817844, 2014). "The induction of oxidative stress, reduction of BDNF and serotonin, and attenuation of CREB signaling by prenatal exposure to a supra-therapeutic dose of buprenorphine provides evidence of a potential mechanism for the development of depression-like neurobehaviors." (PMID 24367510, 2013). "Although BDNF has undoubtedly received the most attention, emerging and recent evidence indicates that other growth factors, most notably glial cell-line derived neurotrophic factor (GDNF) (a member of the transforming growth factor beta family) is also likely involved in depression." (PMID 24312008, 2013). "This, however, does not appear to be the case here as four of the five included studies found that the presence of past and/ or current depression did not have a significant effect, while the fifth study found BDNF levels were in fact elevated in patients with MDD." (PMID 23908608, 2013). "Serum BDNF was found to be significantly reduced in antidepressant-naïve depression patients compared to those who were treated with antidepressants and there was a significant negative correlation between BDNF levels and the Hamilton Rating Scale for Depression." (PMID 23847583, 2013). "Furthermore, it is well-known that neurotrophic factors such as brain derived neurotrophic factor (BDNF) and fibroblast growth factor (FGF) play an important role in the etiology of mood disorders, such as depression, and in modulating emotional responses, including anxiety." (PMID 24058337, 2013). "Our results show that, after a period of stress, which induces a depression-like phenotype, mice exposed to a favorable environment, such as enrichment, recovered when treated with FLX, displaying reduced anhedonia, higher brain BDNF levels and lower corticosterone levels compared to controls." (PMID 23653679, 2013). "However, the fact that a lack of BDNF signaling negated the effects of antidepressant treatment argues that whilst it is not predictive of depression, it is integral for the potency of antidepressant action." (PMID 23847583, 2013). "Thus, similar to the case of BDNF, it appears that the relationship between GDNF and depression may be more nuanced and complex than perhaps initially thought, and compensatory processes are likely involved." (PMID 24312008, 2013). "In addition to BDNF, other trophic factors, including glial derived neurotrophic factor (GDNF) and fibroblast growth factor (FGF-2), might also play a role in depressive disorders." (PMID 24019878, 2013). "Finally, depression, which is common in patients with severe COPD, could reduce BDNF serum concentrations in patients with severe COPD." (PMID 23245944, 2012). "Increased BDNF levels support the neurotrophic hypothesis of depression, but our findings do not clearly evidence that the BDNF response after triple reuptake inhibitors is more effective than after dual reuptake inhibitors." (PMID 22581450, 2012). "However, findings fail to support the view that a simple lack of BDNF or an incapacity for neurogenesis in the hippocampus redounds in depression." (PMID 22912626, 2012). "It is likely that the lack of correlation between mature BDNF levels and depression severity seen in our study may be due to the absence of severe disease patients within our cohort." (PMID 22880079, 2012). "However, given that blocking neurogenesis in the hippocampus or preventing the expression of BDNF fails to create depression, suggests that lack of capacity for neurogenesis in the hippocampus is not sufficient to cause depressed behavior." (PMID 22912626, 2012).
depression (continued). "Human studies report that BDNF levels are a reliable biomarker for depression, where there is a strong negative relationship between peripheral BDNF levels and depression and treatment of depression might result in an increase in serum BDNF." (PMID 23304508, 2012). "While neither proBDNF nor mature BDNF serum levels was associated with clinical variables, there were significant correlations between MMP-9 serum levels and the severity of depression, quality of life scores, and social function scores in patients." (PMID 22880079, 2012). "Notably, we found that plasma BDNF concentrations were significantly different between the remission and non-responder groups at the depressive syndrome stage." (PMID 22761741, 2012). "Interestingly, plasma BDNF levels in the non-responder group were significantly higher than those in the remission group in the initial stage of depressive syndrome (p = 0.002)." (PMID 22761741, 2012). "To determine whether plasma BDNF levels could predict treatment outcome, we examined plasma BDNF levels in the remission and non-responder groups at the initial depressive syndrome stage." (PMID 22761741, 2012). "In the present study, we were able to accurately distinguish between patients with major depression and healthy controls, based on the methylation profiles of CpG units within CpG I, but not CpG IV, of the BDNF gene, and these results were completely concordant with clinical diagnoses." (PMID 21912609, 2011). "The authors suggested that although BDNF levels were not able to distinguish between lethal and non-lethal suicide attempts, a reduction of plasma BDNF level may be considered as a biological marker of suicidal depression." (PMID 21441870, 2011). "Thus, negative emotional interventions, such as stress or depression animal models, have shown to impair neurogenesis as well as BDNF expression in the hippocampus." (PMID 22654714, 2011). "Then, whereas increased expression of CREB and BDNF in the hippocampus reverses stress-induced changes in this structure, increased expression of CREB and BDNF in the nucleus accumbens increases learned helplessness and social defeat in animal models of depression." (PMID 21267376, 2010). "However, the comparison of BDNF and ProBDNF between AG and BG suggested no obvious distinctions, indicating that the levels of these factors may be more affected by the overall state of depression rather than by SS alone." (PMID 40821647, 2025). "Endocan and BDNF levels were notably lower in individuals with clinically relevant anxiety (p = 0.047 and p = 0.016, respectively), while differences in participants with and without clinically relevant depression were not statistically significant (p = 0.061 and p = 0.474, respectively)." (PMID 40491453, 2025). "Finally, we could not explore the mechanisms for improving postoperative depression and pain, as only one study assessed the perioperative serum BDNF and 5-hydroxytryptamine levels." (PMID 40223927, 2025). "Therefore, we can expect BDNF to be an effective mediator between physical activity and AHN, as even when hippocampal volume is used as a dependent variable instead of its actual count in humans, the dependencies of increased cognitive function and reduced depression proves its mediating role." (PMID 39595896, 2024). "So the administration of asiaticoside to depression-like mice restored the composition of the gut microbiota, could improve intestinal permeability and blood-brain barrier integrity, then could decrease the levels of IL-6, TNF-α, CRH, and CORT and increase hippocampal BDNF levels." (PMID 39494347, 2024). "Furthermore, ghrelin/GHSR can activate multiple signaling pathways, including cAMP/CREB/BDNF, PI3K/Akt, Jak2/STAT3, and p38-MAPK, to produce antidepressant effects, given which it is expected to become a potential therapeutic target for the treatment of depression." (PMID 39057075, 2024).
depression (continued). "Furthermore, the overall metabolic health of females and improper neuronal development in the absence of BDNF may also lead to depression and early aging." (PMID 38982490, 2024). "Therefore, it is plausible that BDNF and NGF, which were found to be upregulated here, could mediate the improved cognitive function and the reduced depression/anxiety-like behavior observed at long-term post-reperfusion by the combined Zn and Se administration or Zn administration alone." (PMID 38707461, 2024). "In addition, BDNF could also bind to TrkB receptors, activating other signaling pathways, such as phosphatidylinositol 3-kinase (PI3K)/Akt and MAPK signaling pathways, which play a role in mood disorders and depression." (PMID 36973813, 2023). "Moreover, several studies have demonstrated an increase in BDNF mRNA expression in the BLA after exposure to different types of stress (intermittent water immersion stress, restraint, fear conditioning), suggesting specific regional protein involvement with anxiety- or depression-like behaviors." (PMID 37895171, 2023). "Moreover, the action of BDNF may be brain region dependent—in the ventral tegmental area (VTA) and nucleus accumbens (NAc), BDNF exerts a potent pro-depressant effect, and the direct infusion of BDNF into the VTA–NAc increases depression-related behaviours." (PMID 36902200, 2023). "Moreover, sodium butyrate was reported to improve aversive memory impairment, depression-like behaviors, and hippocampal microglial activation via inhibiting histone deacetylase and increasing the levels of Ten-Eleven Translocation 1 (TET1), 5-HT, and BDNF expression." (PMID 37759312, 2023). "Interestingly, 26 weeks of daily intake of n-3 PUFFA increased plasma BDNF levels; however, it showed a significant negative correlation between change in BDNF (at baseline and at the end of the study) and the score of the Calgary Depression Scale for Schizophrenia (CDSS)." (PMID 36767478, 2023). "However, under the CUMS-induced depression-like conditions, the usage of BDNF-shRNA could not further enhance the immobility of mice exposed to CUMS, as we think there was a maximum limit for animal behaviors in the 2 tests." (PMID 37603290, 2023). "Following this assumption, the lower serum BDNF levels in PSD could indicate a breakdown of the stress adaptation system and its failure to protect the brain from stress-induced neuronal degeneration, which consequently sets the stage for the development of depression." (PMID 37895349, 2023). "Interestingly, BDNF levels have been shown to be significantly reduced in the serum of PD patients with depression compared to those without depression, although a recent meta-analysis did not observe significant associations between serum BDNF levels and depressive symptoms in PD." (PMID 37374342, 2023). "Furthermore, in mouse studies, SNK ingestion enhanced mRNA expression of neurotrophic factor (BDNF), neurotrophin-3, and gamma-aminobutyric acid (GABA) receptors under stress-free and chronic social stress conditions, and showed a tendency to improve learning ability and depression-like behavior." (PMID 35897310, 2022). "Therefore, the study aimed to investigate differences in concentration of BDNF and proBDNF in patients with OSA and healthy participants, to evaluate their diurnal changes, and to assess their correlations with insomnia and depression symptoms that might contribute to specific OSA phenotypes." (PMID 36498709, 2022). "The enhanced neuroinflammatory response may mediate the pathogenesis of depression by triggering a variety of downstream pathogenesis processes, such as impairment of the monoamine system and cyclic adenosine monophosphate (cAMP)-response element binding protein (CREB)-BDNF signaling." (PMID 36188580, 2022).
depression (continued). "It was also proposed that a negative spiral of low BDNF levels and impaired 5-HT signaling may lead to a reduction of brain resilience to environmental challenges, with crucial implications for neuropsychiatric disorders such as depression." (PMID 35420371, 2022). "Furthermore, the basal PFC BDNF protein was lower in males than in females in non-depressed controls, which may be explained by sex differences in the epidemiology of depression and suicidal behaviors." (PMID 36611538, 2022). "Interestingly, PIP-mediated anti-depressant activity involves BDNF/TrkB signaling cascade as well, and chronic treatment of PIP could increase BDNF protein concentration in the hippocampus and cortex of the mouse model of depression." (PMID 35052833, 2022). "rTMS increased serum BDNF levels and decreased serum IL-1b and TNF-a levels inpatients with depression but had no effecton any of these factors in healthy individualsResults suggest that rTMS may increase BDNF and decrease IL-1b and TNF-a serum levels in elderly patients with refractory depression." (PMID 35735405, 2022). "Thus, CRS may cause a decrease in BDNF levels in the hippocampus, which leads to a decrease in Narp expression, resulting in depression-like behaviors in mice, whereas (2R,6R)-HNK exerts its antidepressant-like actions via BDNF/TrkB receptors and the Narp pathway in the hippocampus." (PMID 35291971, 2022). "Moreover, currently we could not determine that BDNF is the only antidepressant target for oroxylin A yet, since the pathophysiology of depression involves dysfunction of many other systems besides monoaminergic and neurotrophic deficiency." (PMID 35959431, 2022). "The changes in molecules such as IκB-α, NF-κB, JNK, Nrf2, Akt, AMPK, CREB, and BDNF may mediate the effects of sinomenine in CNS disorders, including cerebral ischemia, intracerebral hemorrhage, TBI, AD, PD, epilepsy, sleep disturbance, depression, multiple sclerosis, and morphine tolerance." (PMID 36188580, 2022). "Similarly, a study found that the acute effect of lamotrigine augmentation therapy for patients with treatment-resistant depressive disorder is not related to BDNF, suggesting the BDNF expressions show different change trends with different depressive conditions." (PMID 35295780, 2022). "Finally, as a further test of the hypothesis for an extended ARMS phenotype, we submitted PQ‐B total symptoms scores along with BSI anxiety and depression measures to a 2 × 2 MANOVA with two between‐subjects factors of serotonin (long, short) and BDNF (Val/Val, Met)." (PMID 33932264, 2021). "Moreover, our previous studies had demonstrated that depression induced by chronic stress could generate disorder of hippocampal blood oxygen level dependent (BOLD) signals, accompanied by the reduction of BDNF level and the number of adult neurons in the dentate gyrus." (PMID 33591947, 2021). "Accumulating evidence has implicated that brain derived neurotrophic factor (BDNF) is thought to be involved in the pathophysiology of depression, but its correlation with ketamine’s antidepressant efficacy focusing on Chinese individuals with depression is not known." (PMID 33850645, 2021). "Some previous studies predicted the molecular mechanism on depression of BXHPD, which mainly included activation of the inflammatory response system, monoamine hypothesis, Hypothalamic Pituitary Adrenal (HPA) axis dysfunction, low expression of brain-derived neurotrophic factor (BDNF) and so on." (PMID 32997725, 2020). "Since BDNF influences neuronal survival, mood, and long-lasting memory formation and intensifies synaptic plasticity with neuro-regenerative effects by weakening the processes of neuronal degeneration, SGK1 may contribute to several BDNF-dependent neuropsychiatric disorders including depression." (PMID 32849818, 2020).
depression (continued). "Moreover, according to the relevant mechanisms reported in preclinical studies, whether the change in BDNF can be inhibited to treat comorbid depression and addiction has not been clarified." (PMID 32694984, 2020). "In patients with DM and depressive disorders, a wide variety of disturbances may affect the central nervous systems, including the overactivation of the HPA axis, decreased monoamine neurotransmitters, and dysfunctional brain-derived neurotrophic factor (BDNF)." (PMID 33568996, 2020). "In this analytical cross-sectional study, the serum BDNF levels were measured in peripheral blood samples of 20 consecutive acne vulgaris patients with depression and 98 consecutive acne vulgaris patients without depression and also compared it with a 59 healthy control group by using a ELISA." (PMID 31234814, 2019). "Although animal studies showed a decrease in BDNF level was not sufficient to produce depressive-like behaviors, clinical evidence showed that there was a reduction in BDNF levels with neuronal dysfunction in the brains of patients with major depressive disorder." (PMID 31881712, 2019). "Finally, this study provides the first demonstration of the involvement of PAI-1 in depression by a mechanism independent of BDNF, and suggests that PAI-1 could be an innovative target for the development of new drugs for MDD." (PMID 31610810, 2019). "Interestingly, SGK1 reported a negative correlation with BDNF, which may evoke a potential mechanism of impaired neurogenesis in depression." (PMID 31540539, 2019). "However, the therapeutic effects of VD3 on the chronic unpredictable mild stress (CUMS) model of depression, and whether the antidepressant-like action of VD3 involves BDNF, neurotrophin-3 (NT-3), neurotrophin-4 (NT-4), and the HPA axis in long-term OVX adult rats remain unknown." (PMID 31357443, 2019). "Exercise-mediated alleviation of CUMS-induced depression-like behaviors, and reversal of CUMS-induced decrease in spine density in the hippocampus, may result partly from reversal of the CUMS-induced decrease in the BDNF level and increase in the pro-BDNF level by exercise." (PMID 31130853, 2019). "Therefore, our results indicated that the depression-like behaviors in the young and adult rats which experienced early life stress could be alleviated different doses of SNS by regulating the 5-HT1A receptor/CREB/BDNF signaling pathway." (PMID 30984042, 2019). "Taking together the evidence in AN of elevated pro-inflammatory cytokines, reduced concentrations of BDNF and VEGF-A, and reduced hippocampal volumes, a key area for adult neurogenesis, it could be hypothesised that this mechanism may be at play in AN, as proposed in the depression literature." (PMID 30355978, 2018). "Moreover, recent reports have demonstrated that female mice lacking ERβ leads to dysregulation of brain-derived neurotrophic factor and serotonin signaling and decrease synaptic plasticity in the HPC, which could predispose the brain to a state of depression." (PMID 29362726, 2018). "Furthermore, the difference in BDNF concentrations in platelet-rich plasma between AD patients and healthy subjects, found by Platenik and colleagues, has been confirmed in patients with depression, but not in those without it." (PMID 29330839, 2018). "Although treatment with major classes of antidepressants can increase peripheral BDNF levels, not all MDD patients benefit from antidepressant treatment, and the symptoms of depression occasionally deteriorate after antidepressant administration." (PMID 29348904, 2017). "Considering that MS15 did not significantly reduce the BDNF or NF-L expression in the hippocampus of normal mice, we concluded that MS induced the depression-like behavior as a result of the decreased expression of these plasticity-related proteins; thus, neuroplasticity may be inhibited." (PMID 26798520, 2015).